BRAF (B-Raf proto-oncogene, serine/threonine kinase)
Diseases named in the same sentence as BRAF in open-access papers (continued):
Sharing a sentence is not in itself a finding about the gene and the disease.
Histiocytosis (21 papers, 2014 to 2025). An excessive number of histiocytes (tissue macrophages). "The identification of mutations affecting members of the MAP-kinase pathway in histiocytosis lesions is important both to confirm the diagnosis and to identify possible therapeutic targets (e.g. BRAF-V600E mutation, MEK inhibition)." (PMID 38718824, 2024). "The discovery of the recurrent BRAF gene mutation's involvement in histiocytosis pathogenesis is relatively recent." (PMID 39190425, 2024). "This is why we have conducted a retrospective study of all patients with clonal histiocytosis in our institution and present the data according to the presence of BRAF mutation." (PMID 37809108, 2023). "Most of the mutation in histiocytosis is BRAF V600E in subtypes." (PMID 38376733, 2025). "However, among the various other types of histiocytosis, considerable amount of work is done on LCH, one of the prominent types of histiocytosis, such as, the roles and implications of BRAF mutations in LCH pathogenesis." (PMID 38376733, 2025). "Additionally, Brazil lacks epidemiological data on histiocytosis and studies evaluating the budgetary impact of incorporating BRAF mutation research and the use of vemurafenib into the public health care system." (PMID 39190425, 2024). "However, extracutaneous JXG lesions with mitogen activated pathway kinase (MAPK) / extracellular-signal-regulated kinase (ERK) pathway activating mutations are now categorized into the Langerhans “L-group” histiocytosis, including three rare BRAF V600E JXG “L-group” neoplasm." (PMID 31685033, 2019). "Xenotransplantation of CD34 + HSPCs from BRAF mutant patients with histiocytosis (ECD or MH) resulted in the development of histiocytosis-like lesions and detection of BRAF V600E in circulating monocytes of ECD and mixed histiocytosis patients." (PMID 39592527, 2024). "Phase II trial aiming to optimize the dose and timing of vemurafenib in patients with BRAF positive refractory histiocytosis." (PMID 37965340, 2023). "The knowledge of BRAF and other MAPK pathway mutations has led to the use of BRAF and MEK inhibitors in prospective clinical trials of histiocytosis, including a small proportion of participants who have CNS LCH." (PMID 37519792, 2023). "Owing to the co-occurrence of ECD with LCH in 15% of patients with ECD and the discovery of BRAF mutations and of other MAP kinase pathway alterations, LCH and ECD belong to the “L” group in the 2016 revision of the classification of histiocytosis." (PMID 35115034, 2022). "They advised long-term follow-up to determine if pediatric BRAF V600E positive CNS-JXG is a distinct entity in the L-group histiocytosis category or represents an expanded pediatric spectrum of ECD." (PMID 34178890, 2021). "Future studies with long-term follow-up are required to determine if pediatric BRAF V600E positive CNS-JXG neoplasms are a distinct entity in the L-group histiocytosis category or represent an expanded pediatric spectrum of ECD." (PMID 31685033, 2019). "Besides, because of the overlapping image pattern and association of different types of histiocytosis, histopathological or even genetic testing, for example for BRAF mutations, is still recommended for distinguishing RDD from other histiocytosis." (PMID 37179326, 2023). "In addition, there is a lack of epidemiological data on histiocytosis in Brazil and studies evaluating the budgetary impact of incorporating BRAF mutation research and the use of vemurafenib into the public health system." (PMID 39190425, 2024). "Additionally, we noted that the presence of CD1a-positive cells in primary cultures of sl-pHCs was not correlated with BRAF mutation, histiocytosis type, or disease outcome." (PMID 38342891, 2024).
Histiocytosis (continued). "This study specifically excluded such cases, including mixed histiocytosis, which needs further investigation to understand whether BRAF V600E mixed pediatric CNS LCH-JXG lesions also share a common hematopoietic precursor, similar to adult BRAF V600E LCH-ECD histiocytosis." (PMID 31685033, 2019).
lung squamous cell carcinoma (21 papers, 2014 to 2026). "As an example, genetic analysis has become an established part in the standard diagnostic workflow of lung squamous cell cancer, and BRAF- and MEK-inhibitors dabrafenib and trametinib are approved as palliative first-line therapy in BRAF-mutated cancer." (PMID 40427091, 2025). "In a histology-independent trial of the BRAF inhibitor vemurafenib, a cohort of patients with non-squamous cell lung carcinoma harboring the BRAF V600E mutation demonstrated a 42% partial response rate after treatment with vemurafenib." (PMID 39234402, 2024). "Tumor heterogeneity, especially in the metastatic phase, is influenced by various factors including histological subtypes (such as adenocarcinoma and squamous cell lung cancer) and genetic mutations (such as those in EGFR, BRAF, KRAS, and ALK translocations)." (PMID 39518079, 2024). "The EZH2 gene expression of lung squamous cell carcinoma was positively correlated with the gene expression of BRAF (r = 0.3662, p < 0.0001) and KRAS (r = 0.3567, p < 0.0001)." (PMID 37069494, 2023). "In 96 lung squamous cell carcinoma blood samples, there were 8 (8.3%) EGFR mutations, 7 (7.3%) KRAS mutations, 6 (6.3%) PIK3CA mutations and 1 (1.0%) BRAF mutations." (PMID 31749831, 2019). "In 134 lung squamous cell carcinoma tissue samples, there were 7 (5.2%) EGFR mutations, 6 (4.5%) KRAS mutations, 12 (9.0%) PIK3CA mutations, 1 (0.7%) BRAF mutations and 1 (0.7%) MET amplifications." (PMID 31749831, 2019). "Datasets like TCGA lung squamous cell carcinoma (LUSC) show mutational incidents of BRAF in more than 5% of the patients but not a single substitution of c.1799T>A." (PMID 25600636, 2015).
ovarian tumors (20 papers, 2009 to 2026). "It is noteworthy that recent studies suggest that KRAS/BRAF mutations play critical roles in the subtyping and prognosis of ovarian tumors, pointing toward future directions for integrating radiomics with molecular biomarkers." (PMID 41601780, 2026). "Since mutations in the MAPK/ERK pathways are common in both borderline and low-grade ovarian cancer and luminal breast cancers the presence of KRAS and BRAF mutations was investigated among the ovarian tumors." (PMID 25226589, 2014). "Screening BRAF mutations may be helpful in classifications of ovarian tumors and selection an appropriate treatment." (PMID 37600581, 2023). "Molecular analysis detected the BRAF K601E mutation in ovarian tumor tissues." (PMID 31952290, 2020). "Our data showed mutual exclusivity between the molecular event of PIK3CA amplification and mutations in PIK3CA, KRAS, BRAF genes, which suggests that each of these alterations may individually be sufficient to drive ovarian tumor pathogenesis independently." (PMID 19638206, 2009). "As for genetic alterations characteristic of less aggressive ovarian tumors, the genes with the highest number of polymorphisms in BOTS and lgOvCa compared to hgOvCa were KRAS, BRAF, and NRAS, which is in line with the scientific literature." (PMID 39456660, 2024). "In low-grade ovarian tumours, mutations in the MAP3K BRAF gene constitutively activate the downstream kinase MEK." (PMID 26456302, 2015). "In low-grade ovarian tumors, BRAF inhibitor use has been also proposed." (PMID 36967525, 2023). "Our previous study demonstrated that although KRAS and BRAF mutations never coexisted within the same ovarian tumor, a defect in one of those genes was present in 6 out of 7 SBOTs examined with the Idylla Mutation Test." (PMID 29682098, 2018). "We examined the expressions of TIMP3, BRAF, and ITGB1 in ovarian tumor samples from both the LLU cohort and, subsequently, confirmed these findings using the TCGA database, stratified by race." (PMID 41294900, 2025). "Our dot blot analysis revealed that in highly aggressive ovarian tumors (hgOvCa), CRNDEP level was significantly increased compared to BOTS without the BRAF V600E mutation (BOT)." (PMID 39062774, 2024). "Hyperactivation of MEK1/2 and ERK1/2 is often caused by activating mutations in Kirsten rat sarcoma viral oncogene homolog (KRAS) and V-Raf murine sarcoma viral oncogene homolog B (BRAF) genes, and therefore was considered to be confined to low-grade ovarian tumors only." (PMID 36362153, 2022). "SPAG5 mRNA expression was lowest in wild-type (BRAF/KRAS/ERBB2) ovarian tumors, which differed from nonmutant tumors (P < 0.001) and wild-type (BRAF/KRAS) tumors (P < 0.001)." (PMID 31985007, 2020). "Certain mutations seem to play an important role in BOTS without the BRAF V600E variant (KRAS) and in lgOvCa (KRAS and NRAS), but not in hgOvCa, once again proving that advanced OvCa are molecularly distinct from less aggressive ovarian neoplasms." (PMID 39456660, 2024).
renal cell carcinoma (20 papers, 2007 to 2025). "Lung adenocarcinoma, renal cell carcinoma, tumors with ALK rearrangement, HER2 amplification, and BRAF V600 mutation had increased risks of RN." (PMID 40563819, 2025). "Renal cell carcinoma, colorectal cancer, sarcoma, and BRAF positive melanoma are considered relatively radioresistant." (PMID 40563819, 2025). "BRAFV600E gene mutations are frequently detected in a wide range of benign and malignant human tumors, however, BRAF mutations in renal tumors such as renal cell carcinoma (RCC), oncocytoma, and WT are essentially absent." (PMID 33046021, 2020). "Mutations in the BRAF gene are rare in renal cell carcinoma, and thus, BRAF inhibitors are not considered standard in the treatment of these cancers." (PMID 26918217, 2016). "It is of interest that Sorafenib is active against renal cell carcinoma, a tumour that does not frequently have BRAF mutations, suggesting that some of its clinical activity may be directed against non-RAF targets." (PMID 17179987, 2007). "These pathways included some already known phosphoproteins involved in renal cell carcinomas, such as PAK1, PAK2, and BRAF." (PMID 36997065, 2023). "The renal cell carcinoma pathway included some already known phosphoproteins involved in RCC, such as PAK1, PAK2, and BRAF." (PMID 36997065, 2023). "Renal Cell Carcinoma Pathway assigned of 49/66 CNA genes RAF1 (16/26) and VHL (14/26) as G1 top-ranks with Fisher’s exact test p-values of 0.00228 and 0.0004437 (respectively) and SOS2 (7/20), HGF (4/20) and BRAF (3/20) as G3 top-ranks with p-values of 0.17, 0.51 and 0.075, respectively." (PMID 28486536, 2017).
triple-negative breast carcinoma (20 papers, 2015 to 2024). An invasive breast carcinoma which is negative for expression of estrogen receptor (ER), progesterone receptor (PR), and human epidermal growth factor receptor 2 (HER2). "For this purpose, we used MDA-MB-231 cells, the most commonly used triple-negative breast cancer cell line model, which carry mutations in Ras effector pathway (BRAF and NF1 mutations)." (PMID 38383288, 2024). "As a point of reference colorectal cell lines with BRAF mutations, which would be regarded as sensitive in general have IC50s for refametinib ranging from 50nM to >1000 nM, whilst the triple negative breast cancer cell line MDAMB231 has an IC50 of less than 100nM." (PMID 29156708, 2017). "Clinically, few reports showed a favorable response of metastatic triple-negative breast cancer to the BRAF inhibitor, vemurafenib." (PMID 38919805, 2024). "This study uses a proteolysis targeting chimera (PROTAC) to probe the role of BRAF V600E in colorectal and triple-negative breast cancer cells." (PMID 38136350, 2023). "In this study, we assess the effectiveness of the PROTAC, SJF-0628, in the broader cellular background of heterozygous BRAF V600E-driven CRC and triple-negative breast cancer (TNBC) cell lines." (PMID 38136350, 2023).
anaplastic cancer (19 papers, 2006 to 2025). "In our analysis, SQSTM1-NTRK3 chromosomal rearrangement was identified in one case, and another patient with anaplastic carcinoma harbored a BRAF pathogenic variant." (PMID 38791947, 2024). "The V600E mutation of the BRAF gene was detectable only in papillary cancers (58.7%; n = 63) and anaplastic cancers (40%; n = 10)." (PMID 33440616, 2021). "A study examining a larger number of samples is essential to clarify the role of the BRAF mutation in anaplastic carcinoma." (PMID 17453004, 2007). "When multi-step carcinogenesis is taken into account, a considerable number of anaplastic carcinomas with BRAF mutations should be found." (PMID 17453004, 2007). "Overall, we propose that PD-L1, BRAF V600E, and MMR protein immunohistochemical staining should be performed for all SWI/SNF-deficient undifferentiated carcinomas." (PMID 38217014, 2024). "Another patient, diagnosed with undifferentiated carcinoma with a BRAF V600E alteration, underwent trametinib treatment as a third-line regimen, showing a PFS of 1.8 months." (PMID 38520742, 2024). "Here, we report the first case of a SMARCB1-deficient undifferentiated carcinoma expressing high PD-L1 and responding to a PD-1 inhibitor, with low tumor mutation burden (TMB), proficient mismatch repair (MMR) and BRAF V600E mutation in the rectum." (PMID 38217014, 2024). "In clinical practice, dual therapies with a BRAF inhibitor and a MEK inhibitor are being recommended in anaplastic cancers with the BRAFV600E mutation." (PMID 36765665, 2023). "While the majority of WDTC have a simple genetic background, with recurrent mutations in BRAF and RAS genes, poorly differentiated and anaplastic cancers are often characterized by multiple co-occurring mutational events." (PMID 33799953, 2021). "A 62-year-old Norwegian woman, with a fast growing lump in her left groin, was primarily diagnosed as having undifferentiated carcinoma that was BRAF V600 positive." (PMID 28343447, 2017). "Here, we report the first case of a SMARCB1-deficient undifferentiated carcinoma in the rectum expressing high PD-L1 and responding to a PD-1 inhibitor, as well as with low tumor mutation burden (TMB), proficient mismatch repair (MMR) and BRAF V600E mutation." (PMID 38217014, 2024). "Transgenic mice models show that PIK3CA (p.H1047R) and BRAF p.V600E co-mutation induce epithelial–mesenchymal transition (EMT) in the tumor, which in turn is associated with decreased mouse survival and transition from well-differentiated thyroid tumors to anaplastic carcinoma." (PMID 41175860, 2025). "The BRAF V600E mutation was found in 142 (83 %) of 172 PTCs without distant metastasis, 15 (56 %) of 27 PTCs with distant metastasis, 1 (14 %) of 7 poorly differentiated carcinomas and 4 (80 %) of 5 anaplastic carcinomas." (PMID 26857243, 2016). "The incidence of BRAF V600E in anaplastic carcinomas is similar to that in early-stage well-differentiated tumors, suggesting that some anaplastic carcinomas develop from PTC and that BRAF signaling may be important in this process." (PMID 22654559, 2011). "Since MAPK activation in BRAF p.V600E- or RAS-mutated tumors increases TERT transcription, BRAF p.V600E or RAS co-mutation with TERT has been strongly associated with advanced disease and poor outcome, even in aggressive tumors, such as high grade non-anaplastic and anaplastic carcinoma." (PMID 41175860, 2025).
histiocytic neoplasm (19 papers, 2017 to 2025). Histiocytic tumors are a heterogeneous group of tumors and tumorlike masses commonly associated with histologically identical extracranial lesions. "BRAF V600E mutations have also been identified in a subset of marginal zone lymphomas as well as some histiocytic neoplasms." (PMID 33801781, 2021). "Another study by Bubolz and colleagues concluded that BRAF mutations in histiocytic neoplasms are restricted to the Langerhans-cell type, although HS was not included in the study." (PMID 28376906, 2017). "This review covers the current understanding of histiocytic neoplasms, molecular pathophysiology, with a particular focus on mutations in genes such as BRAF, MAP2K1, and the PI3K-AKT signaling pathways, and evolving treatment strategies, especially focusing on LCH, ECD, RDD, and JXG." (PMID 38963520, 2024). "However, while both MEK and BRAF inhibitors have been associated with high overall response rates in histiocytic neoplasms, immediate toxicity, the potential for delayed toxicity, and cost become increasingly important factors as continuous therapy appears to be necessary for a durable response." (PMID 40546505, 2025). "Assessments by IRC, unlike those according to the investigators in previous studies of MEK or BRAF inhibitors in patients with histiocytic neoplasms, added to the validity of the findings in this study." (PMID 41035796, 2025). "The physiological role of BRAF in the monocytic-macrophage/dendritic cell lineage remains ill-defined, but somatic BRAF and MEK mutations are increasingly found in histiocytic neoplasms and represent a target for inhibitors blocking these kinases." (PMID 35965494, 2022). "We further posit whether patients with BRAF V600E-mutant AML may benefit from the combined use of BRAF inhibitors and/or RAS-pathway-targeting regimens, which are currently FDA-approved for the treatment of BRAF V600-mutant solid tumors and BRAF-mutant histiocytic neoplasms." (PMID 39596583, 2024). "Trametinib is another MEK inhibitor approved for BRAF V600-mutant melanoma, non-small cell lung cancer, and anaplastic thyroid cancer, and has shown activity in MAPK-driven histiocytic neoplasms, including hairy cell leukemia." (PMID 40546505, 2025). "The BRAF gene, a key player in the MEK-ERK signaling cascade in the MAPK pathway, is notably prevalent in histiocytic neoplasms." (PMID 38963520, 2024). "Moreover, kinase fusions (e.g., involving BRAF, ALK, and NTRK1) have emerged as novel therapeutic targets in histiocytic neoplasms." (PMID 41562669, 2025). "In a recent review of human cases, targeted therapy with a MEK or BRAF inhibitor or dual MEK/BRAF inhibitors used on histiocytic neoplasms has shown benefit to patients with and without a BRAFV600E variant, with treatments lasting over 6 months." (PMID 39202410, 2024). "Moreover, non-LCH histiocytic neoplasms have been reported to exhibit gene fusion involving BRAF (such as RNF11-BRAF and CLIP2-BRAF) and NTRK (such as LMNA-NTRK1)." (PMID 38963520, 2024).